hsa-mir-1253 (hsa-mir-1253 )
Gene: Long non-coding RNA gene on chromosome 17 (2,748,078 to 2,748,182, forward strand). Ensembl gene ENSG00000272920.
Gene Ontology:
Biological process: miRNA-mediated post-transcriptional gene silencing
Cellular component: RISC complex
Homologues: Paralogues in human: MIR1253 (66% identical).